KL (klotho)
Diseases named in the same sentence as KL in open-access papers (continued):
Sharing a sentence is not in itself a finding about the gene and the disease.
diabetes (continued). "Serum Klotho and STRT1 levels decreased in pre-diabetes and returned to normal in diabetic patients." (PMID 34670596, 2021). "The present review summarizes the state of knowledge about the potential role of Klotho in regulating autophagy in Alzheimer’s disease, kidney injury, cancer, COPD, vascular disease, muscular dystrophy and diabetes." (PMID 34737707, 2021). "Thus, the reduced plasma levels of Klotho might contribute to the cardiovascular and renal abnormalities observed in ZO rats, since reduced circulating Klotho also have been reported in other renal or CVDs, including diabetes in humans and mice." (PMID 30483154, 2018). "The reduction in klotho levels has been implicated in a variety of kidney pathological conditions, including diabetic kidney disease (DKD), which is the most prevalent cause of end-stage kidney failure, affecting 30–40% of individuals globally with type 1 or type 2 diabetes mellitus (DM)." (PMID 40119098, 2025). "We conclude that FGF21 levels were significantly higher in patients with DR than non-DR patients with diabetes, and that Klotho levels were significantly lower in patients with DR than non-DR patients with diabetes." (PMID 39257905, 2024). "This study aimed to investigate the relationship between bone metabolism markers, including serum klotho, fibroblast growth factor 23 (FGF23), 25(OH)D3, iPTH, calcium (Ca), and PHOS and the progression of diabetic kidney disease (DKD) in patients with type 2 diabetes mellitus (T2DM)." (PMID 39558979, 2024). "Evidence of mild tubular injury in mice with diabetes and sham IR surgery was demonstrated by an increase in Kim-1 gene expression and a decrease in Klotho gene expression compared with non-diabetic controls." (PMID 38391050, 2024). "The Klotho level in patients with DR was significantly lower than that in non-DR patients with diabetes [SMD: –0.63, 95% CI (–1.22, – 0.04); I2 = 92%]." (PMID 39257905, 2024). "Klotho levels in patients with DR were significantly lower than in non-DR patients with diabetes (SMD: –0.63, 95% CI [–1.22, – 0.04])." (PMID 39257905, 2024). "We only found that Klotho-responders had significantly lower baseline Klotho values than non-responders (p 0.002), a significantly lower percentage of diabetes (p 0.029) and finally that non-responders were predominantly male (p 0.0385)." (PMID 37693766, 2023). "This is consistent with previous studies that showed that serum Klotho levels decrease significantly in diabetic patients, but not in those without diabetes." (PMID 37764740, 2023). "After adjusting for potential confounders, a significant association between the carbohydrate energy percentage and serum Klotho levels was observed in participants who were younger than 60 years old, male, non-obese, and did not have a history of diabetes." (PMID 37764740, 2023). "The RCS plot showed a U-shaped relationship linking serum Klotho levels with diabetes (P for nonlinearity = 0.003)." (PMID 36440221, 2022). "Abnormal downregulation of Klotho has been detected in several aging-related diseases, such as Alzheimer’s disease, kidney injury, cancer, chronic obstructive pulmonary disease (COPD), vascular disease, muscular dystrophy and diabetes." (PMID 34737707, 2021). "The severity of diabetes in our study was not high as we did not include the patients who received treatment for diabetes in the study and HbA1C was about 7.5%, while in studies in which the level of Klotho and SIRT1 reduced, the severity of diabetes was higher." (PMID 34670596, 2021). "Therefore, the primary aim of this study was to evaluate the serum levels of Klotho and SIRT1 in patients with high blood pressure and diabetes and the patients who have both diseases simultaneously." (PMID 34670596, 2021). "In this regard a negative correlation of s-Klotho and HbA1c (lower in established diabetes) is explainable." (PMID 34603200, 2021).
diabetes (continued). "It was reported numerous times that in patients with microangiopathy levels of soluble Klotho are lower and correlated with a degree of renal dysfunction, regardless of the type of diabetes." (PMID 34603200, 2021). "Surprisingly, scientists have found depletion of renal Klotho level in the state of hypertension, diabetes and renal failure, but not after acute myocardial infarction in rats." (PMID 32319182, 2020). "But the level of serum klotho was negative correlation with diabetes mellitus (r = − 0.29, p = 0.011), and the correlation was remain unchanged after adjusted for age (r = − 2.98, p = 0.013)." (PMID 30791885, 2019). "Our in vitro data are however not in favor of these explanations, but rather strengthen our conclusion that diabetes does not influence renal Klotho expression." (PMID 23945089, 2013). "In the context of Klotho, there is also evidence that the blood pressure independent effects of RAS inhibition on cardio‐renal protection in people with diabetes and CKD may be in part be driven by changes in arterial ageing as assessed by Ao‐PWV and increase in levels of Klotho." (PMID 39497615, 2025). "However, there was a significant negative correlation between ABSI and Klotho protein concentration after adjusting for confounding factors, such as smoking, sex, age, diabetes, and alcohol consumption." (PMID 40007807, 2025). "We found a significant negative correlation between the SII and Klotho concentration, which was not affected by sex, race/ethnicity, BMI, smoking status, alcohol consumption, diabetes, CKD, hypertension, COPD, CHD, or hyperlipidemia (all P values for interactions ≥ 0.05)." (PMID 38713671, 2024). "According to our results, diabetes and male gender were more frequent in the non-responder group; therefore, metabolic factors, sex factors and other additional factors are worth exploring as triggers or modulators of Klotho expression." (PMID 37693766, 2023). "As in our model, klotho was knockdown mainly in the pancreas, it may explain the lack of diabetes in this mouse model." (PMID 34944918, 2021). "Vitamin D and FGF23-Klotho signaling pathways have provided important insight into the scientific basis of the TCM theory “Kidneys Govern Bones” and have helped us understand how vascular complications and metabolic bone disorder evolve in CKD and diabetes mellitus." (PMID 27668003, 2016). "Circulating sKlotho concentration may not necessarily reflect total renal Klotho production, and despite similar sKlotho levels in diabetic and non-diabetic individuals, membrane-bound renal Klotho expression might be affected as a consequence of diabetes." (PMID 23945089, 2013). "The sample sizes are as follows: Klotho (High: n = 603, Low: n = 605), age (< 65 years: n = 801, ≥ 65 years: n = 407), renal function by creatinine level (Cr < 133 μmol/L: n = 1165, Cr ≥ 133 μmol/L: n = 43), and diabetes status (No diabetes: n = 947, Diabetes: n = 210, Borderline: n = 51)." (PMID 41495777, 2026). "However, Klotho expression was not altered in the mice after 10 weeks of diabetes." (PMID 36434087, 2022). "Moreover, the widespread use of ACE-inhibitors and angiotensin receptor blockers in the diabetic subjects may have counterbalanced a presumed negative effect of diabetes on Klotho production." (PMID 23945089, 2013). "The results provide further support for the role of PTEN, BECN1, FGF21, Klotho, and CTGF in development albuminuric and non-albuminuric CKD in diabetes." (PMID 38540101, 2024). "The inverse correlation between soluble Klotho levels and the existence of vascular disease, generally accepted in patients with CKD, does not seem to be as evident in subjects with diabetes." (PMID 37686263, 2023). "In STZ-induced diabetes, STZ is toxic to the kidney, not just pancreatic β cells, and it reduces Klotho in the circulation and kidneys." (PMID 35903083, 2022).
diabetes (continued). "The level of Klotho and SIRT1 in patients with combined diabetes and hypertension is not different with those with pure hypertension." (PMID 34670596, 2021). "One study found that the plasma Klotho level was not related to the kidney function in patients with CKD, but this study population included nearly 40% patients with diabetes mellitus (39.4%)." (PMID 23431388, 2013). "The results provide further support for the role of PTEN, BECN1, FGF21, Klotho, and CTGF in the pathogenesis of diabetic kidney disease, and highlight the differences in the molecular pathways of albuminuric and non-albuminuric CKD in diabetes." (PMID 38540101, 2024). "In addition, the relationship between Klotho and the AGE/RAGE pathway has not been studied in animal models of diabetes." (PMID 36982322, 2023).
Hypertension (110 papers, 2012 to 2026). The presence of chronic increased pressure in the systemic arterial system. "Research has shown that higher circulating levels of s-Klotho are associated with better cardiovascular health and a lower risk of diseases such as atherosclerosis, hypertension, and heart failure [1367]." (PMID 40407975, 2025). "The causalities between hypertension, Klotho, and CKD in diabetic patients need further exploration, and underlying mechanisms warrants elucidation." (PMID 40324899, 2025). "Genetic studies in humans suggest that Klotho gene deficiency is associated with vascular calcification, premature bone disease, altered angiogenesis, hypertension, and left ventricular hypertrophy—hallmarks of premature vascular aging." (PMID 39940672, 2025). "Klotho deficiency is mechanistically linked to the development of hypertension through several interconnected pathways involving FGF23, the renin–angiotensin–aldosterone system (RAAS) and sympathetic nervous activity." (PMID 41303567, 2025). "Klotho deficiency is linked to various age-related diseases, including cancer, high blood pressure, and kidney disease." (PMID 41468409, 2025). "The anti-aging gene Klotho is implicated in the pathogenesis of preeclampsia (PE), which is a pregnancy disease characterized by hypertension and proteinuria." (PMID 38632651, 2024). "Upregulation of H3K27me levels downregulates Kl (klotho) gene, which seems to be associated with hypertension." (PMID 39109516, 2024). "Several cohort studies have indicated that decreased serum Klotho levels are associated with conditions, such as heart failure, hypertension, and atrial fibrillation." (PMID 39329104, 2024). "Human studies have shown a significant correlation between blood pressure and klotho protein levels, with higher klotho levels associated with lower risk of developing hypertension." (PMID 39616409, 2024). "The study also suggests that healthcare professionals should consider klotho as a predictive marker in aging-associated essential hypertension patients after certain clinical trials." (PMID 39616409, 2024). "This study aimed to examine the potential association between serum Klotho concentration and hypertension among postmenopausal women in the US." (PMID 37528365, 2023). "In summary, the serum Klotho concentration shows promise as an important predictor for risk stratification in postmenopausal women with an increased susceptibility to hypertension." (PMID 37528365, 2023). "Nevertheless, the precise causal relationship between serum Klotho concentration and hypertension has yet to be confirmed, and thus, it is essential to conduct further prospective cohort studies and clinical trials to elucidate this relationship." (PMID 37528365, 2023). "None of the variables, including age, BMI, smoking, drinking, or hypertension significantly modified the association between serum Klotho and phenotypic age acceleration (all p for interaction > 0.05)." (PMID 38017397, 2023). "The present study primarily investigated the association between serum Klotho concentration and hypertension in postmenopausal women." (PMID 37528365, 2023). "general population, and our findings demonstrate, for the first time, that participants with higher serum Klotho quartiles showed a significantly lower risk of hypertension than those in the first quartile." (PMID 37528365, 2023). "A recent study has indicated that KL deficiency promotes high-fat diet induced arterial stiffening and hypertension via downregulation of AMPKα activity." (PMID 36794161, 2023). "Nevertheless, Klotho has a wide spectrum of cardiovascular benefits, and genetic deficiency of Klotho in mice causes arterial medial calcification, intimal hyperplasia, hypertension, endothelial dysfunction, and even reduced lifespan." (PMID 37894840, 2023).
Hypertension (continued). "This study represents the inaugural examination of the association between serum Klotho protein concentration and hypertension within the postmenopausal women of the US population." (PMID 37528365, 2023). "The findings of this study revealed a significant inverse association between serum Klotho concentration and hypertension among postmenopausal women." (PMID 37528365, 2023). "Postmenopausal women with serum Klotho protein concentration in the second and third quartiles had a reduced probability of 50% and 39% of being susceptible to hypertension compared to those in the lowest quartile." (PMID 37528365, 2023). "Previous research has demonstrated that Klotho deficiencies are associated with numerous aging-related disorders, including renal disease, arteriosclerosis, hypertension, and cancers." (PMID 38027194, 2023). "A recent study has revealed a positive association between higher circulating Klotho protein levels and a decreased incidence of hypertension in older adults aged 70–79 years." (PMID 37528365, 2023). "In another study involving well-functioning older adults, David A. Drew found that higher Klotho levels were associated with a 20% decreased risk of incident hypertension." (PMID 37528365, 2023). "Previous research showed that single nucleotide polymorphisms in the klotho gene are correlated with s-Klotho levels and the susceptibility to hypertension or coronary artery disease, cancer risk and longevity." (PMID 35093938, 2022). "As a result, lower serum Klotho concentration was associated with higher all-cause mortality in patients with hypertension." (PMID 36457804, 2022). "In the Health, Aging and Body Composition Study, low Klotho concentration was associated with a high risk of initial hypertension and high BP trajectories during follow-up." (PMID 36457804, 2022). "It has been shown that Klotho deficiency results in arterial stiffness and hypertension in mice, whereas Klotho supplementation prevents CVD from progressing in mice." (PMID 36457804, 2022). "Accumulating evidence indicates that Klotho gene polymorphisms and serum Klotho concentration are associated with the incidence and development of hypertension." (PMID 36457804, 2022). "The result of two-piecewise linear regression model between serum Klotho concentrations and all-cause mortality and cardiovascular mortality in American adults with hypertension." (PMID 36457804, 2022). "To address the gap in knowledge, we aimed to examine the association between serum Klotho concentration and all-cause and cardiovascular mortality in American patients with hypertension." (PMID 36457804, 2022). "Further large-scale prospective studies are required to verify the relationships between the circulating klotho levels and blood pressure changes and the risk of hypertension in different age groups and disease conditions." (PMID 33504927, 2021). "It has been shown that SIRT1 level is reduced in Klotho deficient rats and activation of SIRT1 attenuates Klotho deficiency-induced arterial stiffness and hypertension." (PMID 34670596, 2021). "A human KL gene point mutation is associated with hypertension and kidney disease, suggesting that KL maintains normal kidney function." (PMID 33767585, 2021). "Few previous studies have indicated that a lower circulating klotho concentration was associated with higher blood pressure or was a risk factor of hypertension." (PMID 33504927, 2021). "A recent study in rats with Klotho haplo-deficiency showed that this genetic defect is associated with arterial stiffening and hypertension and with decreased expression of SIRT1; and activating the SIRT1 gene abolished these defects." (PMID 34670596, 2021). "Serum levels of Klotho are significantly decreased in patients with arterial stiffness and hypertension, and Klotho deficiency has been shown to induce autophagy, which injures vasculature and causes arterial stiffening and hypertension." (PMID 34737707, 2021).